AXL (AXL receptor tyrosine kinase)
Description:
Receptor tyrosine kinase that transduces signals from the extracellular matrix into the cytoplasm by binding growth factor GAS6 and which is thus regulating many physiological processes including cell survival, cell proliferation, migration and differentiation. Ligand binding at the cell surface induces dimerization and autophosphorylation of AXL. Following activation by ligand, AXL binds and induces tyrosine phosphorylation of PI3-kinase subunits PIK3R1, PIK3R2 and PIK3R3; but also GRB2, PLCG1, LCK and PTPN11. Other downstream substrate candidates for AXL are CBL, NCK2, SOCS1 and TNS2. Recruitment of GRB2 and phosphatidylinositol 3 kinase regulatory subunits by AXL leads to the downstream activation of the AKT kinase. GAS6/AXL signaling plays a role in various processes such as endothelial cell survival during acidification by preventing apoptosis, optimal cytokine signaling during human natural killer cell development, hepatic regeneration, gonadotropin-releasing hormone neuron survival and migration, platelet activation, or regulation of thrombotic responses. Also plays an important role in inhibition of Toll-like receptors (TLRs)-mediated innate immune response. (Microbial infection) Acts as a receptor for lassa virus and lymphocytic choriomeningitis virus, possibly through GAS6 binding to phosphatidyl-serine at the surface of virion envelope. (Microbial infection) Acts as a receptor for Ebolavirus, possibly through GAS6 binding to phosphatidyl-serine at the surface of virion envelope. (Microbial infection) Promotes Zika virus entry in glial cells, Sertoli cells and astrocytes. Additionally, Zika virus potentiates AXL kinase activity to antagonize type I interferon signaling and thereby promotes infection. Interferon signaling inhibition occurs via an SOCS1-dependent mechanism.
Synonyms: UFO; JTK11; Tyro7; ARK; AXL3
Tractability: Small molecule: an approved drug acts on it; a structure with a bound ligand is known; a high-quality ligand is known; it belongs to a druggable protein family. Antibody: UniProt places it where antibodies can reach, with high confidence; its Gene Ontology location is reachable by antibodies, with high confidence; UniProt predicts a signal peptide or a membrane-spanning region; the Human Protein Atlas places it where antibodies can reach. PROTAC: UniProt records ubiquitination sites on it; ubiquitination databases record sites on it; a small molecule that binds it is known. Other modalities: a drug acting on it is in phase 2 or 3 trials.
Target class: Tyrosine protein kinase Axl family; Protein Kinase; Kinase; TK protein kinase group; Enzyme
Safety:
Unwanted effects reported when the protein is acted on. In parentheses: how it was acted on, where the effect was seen, and who reports it.
coronary artery disease (source: ClinPGx)
Gene: Protein-coding gene on chromosome 19 (41,219,174 to 41,261,766, forward strand). Ensembl gene ENSG00000167601.
Subcellular location: Cell membrane
Subcellular location (Human Protein Atlas): Plasma membrane; Actin filaments; Vesicles
Pathways (Reactome):
Disease: Dengue Virus Attachment and Entry
Signal Transduction: VEGFA-VEGFR2 Pathway
Gene Ontology:
Molecular function: phosphatidylserine binding; protein binding; protein tyrosine kinase activity; virus receptor activity; transmembrane receptor protein tyrosine kinase activity; ATP binding; protein kinase activity
Biological process: cell maturation; cellular response to interferon-alpha; cellular response to lipopolysaccharide; dendritic cell differentiation; negative regulation of dendritic cell apoptotic process; negative regulation of type II interferon production; phagocytosis; positive regulation of cytokine-mediated signaling pathway; positive regulation of natural killer cell differentiation; positive regulation of pinocytosis; positive regulation of viral life cycle; symbiont entry into host cell; cell migration; cell surface receptor protein tyrosine kinase signaling pathway; natural killer cell differentiation; negative regulation of apoptotic process; nervous system development; platelet activation; positive regulation of phosphatidylinositol 3-kinase/protein kinase B signal transduction; signal transduction; vascular endothelial growth factor receptor signaling pathway; enzyme-linked receptor protein signaling pathway; mononuclear cell differentiation; negative regulation of cytokine production; positive regulation of signal transduction; and 1 more
Cellular component: cell surface; extracellular exosome; extracellular region; plasma membrane; endosome membrane; receptor complex
Genetic constraint (gnomAD): Loss-of-function variants: 54 observed, 108.33 expected, observed/expected ratio (o/e) 0.5, 90% interval 0.4 to 0.62. The upper end of that interval is the gene's LOEUF score, 0.62, which puts it in group 2 of 6, group 1 being the genes least tolerant of losing a copy. Missense variants: 1,024 observed, 1,233.1 expected, observed/expected ratio (o/e) 0.83, 90% interval 0.79 to 0.87. Synonymous variants: 455 observed, 490.66 expected, observed/expected ratio (o/e) 0.93, 90% interval 0.86 to 1.
Homologues: Orthologues: chimpanzee AXL (99% identical), macaque AXL (98% identical), dog AXL (91% identical), pig AXL (89% identical), guinea pig AXL (88% identical), mouse Axl (88% identical), rat Axl (87% identical), rabbit AXL (64% identical), tropical clawed frog axl (59% identical), zebrafish AXL (47% identical). Paralogues in human: MERTK (42% identical), TYRO3 (40% identical), ROS1 (25% identical), MET (25% identical), MST1R (23% identical), IGF1R (22% identical), INSR (22% identical), ALK (20% identical), INSRR (20% identical), TIE1 (20% identical), FGFR2 (20% identical), KDR (20% identical), and 41 more.
Diseases named in the same sentence as AXL in open-access papers:
AXL is named in the same sentence as 294 diseases in open-access papers, as found by Europe PMC text mining. Sharing a sentence is not in itself a finding about the gene and the disease. The quoted sentences say what the papers report.
melanoma (211 papers, 2007 to 2026). A malignant, usually aggressive tumor composed of atypical, neoplastic melanocytes. "Antitumor efficacy was evaluated in AML xenografts and A375 melanoma (AXL overexpression, BRAF V600E mutation)." (PMID 41958931, 2026). "Genetic loss of KLF4 or AXL depletion reduced melanoma cell migration and invasion, suggesting a key role of KLF4 in the regulation of invasiveness." (PMID 41916083, 2026). "AXL expression has been suggested to be associated with epithelial-mesenchymal transition (EMT) in melanoma, which contributes to both metastatic spreading and therapy resistance in cancer." (PMID 38565978, 2024). "Changes associated with MITF and AXL expression patterns in melanoma cells were proposed as means for cells to withstand therapeutic effects by transitioning from one differentiation state to another, which is often referred to as phenotypic switching." (PMID 38672652, 2024). "AXL is linked to the mesenchymal state in the epithelium–mesenchymal transition, while melanoma cells with low AXL expression resemble the epithelial state." (PMID 38790661, 2024). "Research has shown that AXL expression is associated with melanoma dedifferentiation, whereas MITF expression is linked to differentiated tumors." (PMID 37259155, 2023). "In melanoma, AXL expression is associated with an invasive phenotype and thereby resistance to MAPKi." (PMID 35406721, 2022). "Increasing soluble AXL (sAXL) levels in blood has been reported by Flem–Karlsen and colleagues as being associated with melanoma disease progression and correlated with shorter two-year survival in stage IV patients treated with ipilimumab." (PMID 35008245, 2021). "AXL, coding for a receptor tyrosine kinase implicated in melanoma aggressive behavior, was mostly down-modulated." (PMID 33112375, 2021). "The melanoma-associated cluster includes lineage specific genes, such as MITF and MLANA, as well as markers associated with resistance to target therapy in melanoma, such as AXL and NFKB." (PMID 33202944, 2020). "Melanomas characterized by the invasive transcriptional program, associated with high expression of AXL, show intrinsic resistance to BRAF and ERK inhibitors." (PMID 30710146, 2019). "AXL inhibition is shown to be pivotal in overcoming intrinsic or acquired resistance to BRAF/MEK inhibitors by melanoma harboring NRAS and BRAF mutations." (PMID 30651547, 2019). "Expression patterns of transcription factors like microphthalmia-associated transcription factor (MITF) and inversely correlated receptor tyrosine kinases like AXL have been implicated in staging of melanoma with respect to progression and resistance." (PMID 29674683, 2018). "Recently, reduced shedding of AXL has also been implicated in the drug resistance mechanism of TKIs in melanoma." (PMID 28034848, 2017). "> 50% of melanomas progress with enriched “AXL‐high” populations, and because AXL is linked to de‐differentiation and invasiveness avoiding an “AXL‐high relapse” is desirable." (PMID 28606996, 2017). "Low MITF expression in melanomas has previously been linked to increased expression of RTKs such as AXL, EGFR, and PDGFRβ, which activate immediate–early signaling, causing resistance to RAF/MEK inhibitors." (PMID 28069687, 2017). "AXL also regulates melanoma growth and migration and has been implicated in resistance to BRAF inhibition." (PMID 28103611, 2017). "Since loss of MITF is also accompanied by increased invasiveness, it supports previous findings that a high level of AXL expression is associated with a pro-invasive phenotype in melanoma." (PMID 27102439, 2016). "Resistance to the MEK inhibitor, trametinib, was associated with decreased circulating levels of the AXL ectodomain in melanoma patients." (PMID 27834845, 2016). "The secretome of senescent melanoma cells induces a panel of 52 genes, involved in cell movement and cell/cell interaction, among which AXL and ALDH1A3 have been implicated in melanoma development." (PMID 24344100, 2013).
melanoma (continued). "Notably, AXL exhibited significant enrichment in Cluster 2, reinforcing its association with invasive melanoma subtypes." (PMID 40386826, 2025). "While melanoma AXL is associated RAF/MEK inhibitor resistance, it is unknown whether CAF AXL is as well." (PMID 38525245, 2024). "In malignant melanoma, the high level of AXL is mostly associated with the mesenchymal cell state, leading to enhanced resistance to targeted therapy, such as MAPK inhibitors in the case of malignant melanoma and endothelial growth factor receptor (EGFR) inhibitors in case of lung cancer." (PMID 37370757, 2023). "As the increases in STAT3 phosphorylation and AXL expression associated with a decrease in MITF expression have been associated with the resistance of melanoma cells to targeted therapies, we asked whether RICTOR/mTORC2 could play a role in resistance." (PMID 34680615, 2021). "However, AXL was shown to be an upstream effector of the AKT pathway-associated resistance to BRAFi in melanoma with wild-type PTEN." (PMID 34063141, 2021). "Moreover, we identified AXL as a critical upstream effector of AKT pathway-associated resistance to BRAFi in melanoma with wild-type PTEN26,27." (PMID 34282258, 2021). "Upregulation of the receptor tyrosine kinase AXL has been also linked with both a reduced response to immune checkpoint blockade as well as the development of therapy resistance to BRAF directed therapies in melanoma." (PMID 35008245, 2021). "Previous studies have implicated the activation of the AKT pathway by AXL in melanoma." (PMID 32605315, 2020). "In particular, high levels of AXL in melanoma are associated with a transcriptional reprogramming that induces a switch from a proliferative to an invasive phenotype, intrinsically less sensitive to inhibition of the BRAF/MAPK pathway and characterized by low levels of MITF expression." (PMID 33291749, 2020). "Additionally, we observed higher sAXL levels in patients with NRAS mutation compared to NRAS wild type (p value = 0.0143), conferring with a previous report showing higher AXL cellular levels in NRAS mutated melanoma cell lines." (PMID 31917795, 2020). "AXL-targeted ADCs have been evaluated in non-small-cell lung cancer, soft tissue sarcoma, and melanoma, in combination with small molecule inhibitors or immune checkpoint blockade, and Phase I clinical trials with ADCT-601 are ongoing (NCT05389462)." (PMID 39825754, 2025). "The first panel highlights melanoma-associated genes, including MITF, AXL, NGFR, TYRP1, and DCT, which are involved in the regulation of melanoma cell identity, dedifferentiation, and invasive potential." (PMID 40909289, 2025). "The PTEN/AKT/mTORC1/FRA1 signaling axis we previously identified now extends to the regulation of AXL, CDK6, and FSCN1, suggesting that PTEN loss promotes melanoma metastasis partly through this mechanism." (PMID 41286309, 2025). "Analysis of the melanoma TCGA dataset revealed that concurrent alterations of AXL, CDK6, and FSCN1 correlate with poor outcomes of melanoma patients." (PMID 41286309, 2025). "Although MITF-low/AXL-high melanoma subtypes are known to display invasive phenotypes, our data suggest that FRA1 acts independently of direct MITF regulation." (PMID 41286309, 2025). "Several studies have identified AXL as a potential target for new therapies, as its inhibition leads to verified anti-tumor activity in vivo in several types of cancers, including melanoma." (PMID 40869968, 2025). "Central to this axis are MITF and AXL, which act as antagonistic regulators of melanoma cell fate and therapy response." (PMID 41465101, 2025). "The simultaneous delivery of a therapeutic antibody and MAPK inhibitors to AXL-expressing cells has demonstrated efficacy in inhibiting tumor progression in xenograft models derived from melanoma patients." (PMID 41013839, 2025).
melanoma (continued). "In the present study, we demonstrated that, as well as in other cancers, AXL is a direct target of miR-34a-5p in the three melanoma cell lines studied." (PMID 40869968, 2025). "This study showed that circ_0001591 can participate in melanoma migration through the sponging of miR-20a-3p and miR-34a-5p, which, in turn, results in the upregulation of oncoproteins AXL and FRA1." (PMID 40869968, 2025). "Further, AR signaling was reported to drive melanoma invasiveness through tumorigenic fucosylation or the MITF/AXL axis." (PMID 41228208, 2025). "Our data demonstrate that the proportion of MITF+ melanoma cells is significantly decreased upon immunotherapy, while AXL+ melanoma cells seem to be more resistant." (PMID 39697983, 2024). "Recent in vitro studies have shown that the knockdown of AXL by siRNA or its inhibitor bemcentinib in melanoma cells decreased migration and invasion." (PMID 38732242, 2024). "In detail, we observed a strong reduction of AXL levels at the beginning of selection followed by a strong up-regulation when melanoma cells acquired resistance to BRAFi in vitro." (PMID 38472212, 2024). "Melanoma cell lines harboring BRAF or NRAS mutations frequently showed low MITF levels and high AXL-RTK levels." (PMID 38672652, 2024). "Consistent with the negative correlation between the AXL and MITF transcriptional programs in melanoma, we observed an inverse expression pattern between AXL and MITF." (PMID 39697983, 2024). "Our scRNAseq data confirmed the presence of at least two distinct melanoma transcriptional signatures identified by the expression of AXL and MITF." (PMID 39697983, 2024). "Our findings indicate the need of developing novel and alternative therapeutic strategies for targeting treatment-resistant, AXL+ melanoma subpopulations." (PMID 39697983, 2024). "SCRNA seq analysis of 4,600 cells from 19 melanomas revealed that CAF abundance correlated with high AXL/MITF expression in tumor cells." (PMID 38525245, 2024). "In particular, the response of MITF- and/or AXL-expressing melanoma cells to current immunotherapies was investigated, as well as their association with immunological pressure from tumor-infiltrating lymphocytes." (PMID 39697983, 2024). "High tumor AXL expression was frequently present with high CAF AXL levels; and AXL-dependent gene signatures were different in melanoma cells versus CAFs." (PMID 38525245, 2024). "In contrast, the levels of the receptor tyrosine kinase AXL a known marker of acquired resistance to targeted therapies in melanoma, underwent an opposite trend of modulation as compared to mir-579-3p and MITF." (PMID 38472212, 2024). "•Our study shows that MITF+ melanoma subpopulations, are more efficiently targeted by immunotherapy than AXL+ subpopulations." (PMID 39697983, 2024). "In melanomas, AXL-high cells are resistant to MAPK pathway inhibitors, whereas AXL-low cells are sensitive to them." (PMID 38178200, 2024). "This indicates an analogous sensitivity profile of MITF or AXL melanoma cells to both targeted and immunotherapy." (PMID 39697983, 2024). "Previous reports have linked melanoma tolerance to BRAFi with RTK activity (e.g., AXL, FGFR, NGFR, and EGFR) and ERK reactivation." (PMID 39001489, 2024). "Based on these data, we defined AXL+ CD45− CD8− melanoma lineage− cells as potential CAFs, and AXL+ CD45+ CD8− melanoma lineage− cells as potential macrophages." (PMID 39697983, 2024). "Abundance of AXL+ or MITF+ melanoma cells, or AXL/MITF-double-positive cells, showed a weak inverse correlation with the presence of CD8+ lymphocytes." (PMID 39697983, 2024). "In contrast to MITFhigh (MITF+) melanoma cells, which in general are responsive to RAF and MEK inhibitors, melanoma cells expressing high levels of AXL are associated with resistance." (PMID 39697983, 2024). "For example, YAP-mediated melanoma cell invasion was found to require the YAP-dependent induction of AXL, CRIM1, and CYR61." (PMID 38473214, 2024).